BTN3A2 (butyrophilin subfamily 3 member A2)
Description:
Plays a role in T-cell responses in the adaptive immune response. Inhibits the release of IFNG from activated T-cells.
Synonyms: BT3.2; BTF4; BTN3.2; CD277
Tractability: Antibody: UniProt places it where antibodies can reach, with high confidence; its Gene Ontology location is reachable by antibodies, with high confidence; UniProt predicts a signal peptide or a membrane-spanning region. PROTAC: ubiquitination databases record sites on it; its protein half-life has been measured.
Gene: Protein-coding gene on chromosome 6 (26,365,159 to 26,382,797, forward strand). Ensembl gene ENSG00000186470.
Subcellular location: Cell membrane
Pathways (Reactome):
Immune System: Butyrophilin (BTN) family interactions
Gene Ontology:
Molecular function: protein binding; signaling receptor binding
Biological process: positive regulation of type II interferon production; T cell mediated immunity; regulation of cytokine production; T cell receptor signaling pathway
Cellular component: membrane; plasma membrane; external side of plasma membrane
Genetic constraint (gnomAD): Loss-of-function variants: 25 observed, 33.47 expected, observed/expected ratio (o/e) 0.75, 90% interval 0.54 to 1.04. The upper end of that interval is the gene's LOEUF score, 1.04, which puts it in group 4 of 6, group 1 being the genes least tolerant of losing a copy. Missense variants: 264 observed, 386.8 expected, observed/expected ratio (o/e) 0.68, 90% interval 0.62 to 0.76. Synonymous variants: 121 observed, 150.12 expected, observed/expected ratio (o/e) 0.81, 90% interval 0.69 to 0.94.
Homologues: Orthologues: chimpanzee BTN3A2 (91% identical). Paralogues in human: BTN3A3 (90% identical), BTN3A1 (81% identical), BTN1A1 (43% identical), BTN2A2 (41% identical), BTN2A1 (40% identical), BTNL9 (34% identical), BTNL2 (30% identical), BTNL3 (27% identical), BTNL8 (26% identical), MOG (23% identical), ERMAP (20% identical), CD276 (18% identical), and 3 more.
Diseases named in the same sentence as BTN3A2 in open-access papers:
BTN3A2 is named in the same sentence as 48 diseases in open-access papers, as found by Europe PMC text mining. Sharing a sentence is not in itself a finding about the gene and the disease. The quoted sentences say what the papers report.
schizophrenia (9 papers, 2021 to 2026). A major psychotic disorder characterized by abnormalities in the perception or expression of reality. "Previous studies have implicated the role of BTN3A2 as a potential risk gene for Alzheimer's disease, schizophrenia, and intellectual disability." (PMID 39897774, 2025). "Transcriptional imputation of SCZ GWAS summary statistics confirmed the increased expression of C4A, BTN3A2 from xMHC in several brain regions associated with schizophrenia, including dorsolateral prefrontal cortex (DLPFC)." (PMID 35250027, 2022). "Previous studies showed that BTN3A2 was a potential risk gene for Alzheimer’s disease, schizophrenia, and intellectual disability." (PMID 33866329, 2021). "Increased expression of BTN3A2 might confer risk for schizophrenia by altering excitatory synaptic function." (PMID 33412999, 2021). "Moreover, genetic variants in BTN3A2 and C4A were in different LD blocks, suggesting that both genes might be independent risk factors for mental disorders such as schizophrenia and MDD37." (PMID 33866329, 2021). "We identified three genes (BTN3A2, HIST1H2BN and HIST1H4L) that are associated with both SA and major psychiatric disorders, such as MDD, schizophrenia (SCZ), bipolar disorder and autism spectrum disorder, suggesting a potential genetic overlap and pleiotropic effects across these conditions." (PMID 40364472, 2025). "For tier 1 proteins, butyrophilin subfamily 3 member A2 (BTN3A2) and member A3 (BTN3A3) were previously reported as a target gene for schizophrenia, anxiety, cancer, etc.." (PMID 38898508, 2024).
breast carcinoma (8 papers, 2017 to 2022). "BTN3A2 is associated with the prognosis of breast cancer (BRCA) and ovarian cancer (OV), and immunoinfiltration in triple-negative breast cancer (TNBC) and OV is highly associated with BTN3A2." (PMID 35873496, 2022). "In breast cancer, BTN3A2 is an independent prognostic marker for triple negative breast cancer patients." (PMID 34149914, 2021). "The expression level of BTN3A2 is higher in gastric cancer 56, 57, pancreatic cancer 58 and ovarian cancer 59, but lower in breast cancer." (PMID 34149914, 2021). "In HR−/HER2+ breast cancer, four genes (three i-genes BTN3A2, CD2, and TRBC1 and the p-gene MMP11) were significantly associated with distant metastasis-free survival (DMFS)." (PMID 28409241, 2017). "In HR−/HER2+ breast cancer, MMP11 and three i-genes (BTN3A2, CD2, and TRBC1) were significantly associated with clinical outcomes, whereas no clinical variable was significant." (PMID 28409241, 2017). "Furthermore, BTN3A2 expression is itself associated with favorable prognosis in pN0-N1, HR+/HER2− breast cancer." (PMID 28350001, 2017). "Actually, as a crucial mediator in immune activation, butyrophilin subfamily 3 member A2 (BTN3A2) was widely investigated in cancer initiation and development, revealing a tight link between immune infiltration and cancer development, especially in breast cancer (BRCA) and ovarian cancer (OV)." (PMID 35898498, 2022). "Independent prognostic factors for OS in HR−/HER2+ breast cancer included the expression of MMP11 and BTN3A2." (PMID 28409241, 2017). "For example, we showed previously that relative expression of proliferation-related and immune response-related genes, i.e., UBE2C, TOP2A, RRM2, FOXM1, MK167, and BTN3A2, provided a prediction value of adjuvant chemotherapy benefit for patients with ER+/HER2− early breast cancer." (PMID 31779659, 2019). "The higher expression level of BTN3A2 is related to the good prognosis of HR negative, HER2 positive (HR-/HER2+) breast cancer patients, and also to the distant metastasis-free survival (DMFS) rate of breast cancer patients." (PMID 34149914, 2021). "In addition, elevated expression of i-genes (BTN3A2, CD2, and TRBC1) was significantly correlated with favorable clinical outcome in HR−/HER2+ breast cancer, but not in other subtypes." (PMID 28409241, 2017).
ovarian carcinoma (8 papers, 2012 to 2022). A malignant neoplasm originating from the surface ovarian epithelium. "Earlier studies suggested that high BTN3A2 mRNA expression was associated with a good prognosis in relation to disease-free and overall survival in a cohort of 55 epithelial ovarian cancer (EOC) patients." (PMID 26347744, 2015). "Recent studies have found that a higher expression of BTN3A2 in ovarian cancer or triple negative breast cancer is positively correlated with an increased T cell infiltration and a better prognosis." (PMID 33101298, 2020). "Further studies in a larger cohort of 199 high-grade EOC patients confirmed that the protein expression of BTN3A2 in ovarian cancer tissues is positively correlated with the intraepithelial infiltration of CD4+ and CD8+ T cells." (PMID 26347744, 2015). "BTN3A2 is expressed in triple-negative breast cancer, pancreatic ductal carcinoma, and epithelial ovarian cancer, and is associated with a good prognosis." (PMID 35873496, 2022). "Additionally, the expression of BTN3A2 is related to the prognosis of patients with ovarian cancer 15, 42, overall survival and disease-free progression, and its high expression is closely related to the increased overall survival rate of patients." (PMID 34149914, 2021). "In lung adenocarcinoma (LUAD) and epithelial ovarian cancer (EOC), it has been suggested that BTN3A2 expression was positively correlated with CD4+ T cell, neutrophil, B cell, and macrophage infiltration to the tumor area." (PMID 36362212, 2022).
asthma (5 papers, 2020 to 2026). "Increased expression of BTN3A2, one of these genes, in resting T cells is causally associated with a lower risk of asthma development." (PMID 37680636, 2023). "They found that increased expression in resting T cells of Butyrophilin Subfamily 3 Member A2 (BTN3A2) was causally associated with decreased risk of asthma and allergic rhinitis." (PMID 36434743, 2022). "This systematic review found casual effects of BMI, pubertal timing, linoleic acid, alcohol, MDD, immune related proteins ST2, IL1R, CASP‐8, IL6R and BTN3A2 on asthma risk." (PMID 36434743, 2022). "In addition, a protective effect of BTN3A2 expressed in resting T‐cells on asthma and allergic rhinitis was found." (PMID 36434743, 2022). "We also noted family members of butyrophilin (BTN) proteins–immunomodulatory transmembrane proteins involved in recognition of microbial antigens–prioritised in both CD and asthma (BTN3A1 and BTN3A2), specific to ILC3 cells." (PMID 41573945, 2026). "For example, whole blood QTLs related to genes known to affect asthma pathogenesis or severity (e.g. IL18R, ZFP57, BTN3A2, NDFIP1, SMAD3, CLEC16A, and TSLP) were associated with colocalization sites for asthma and neutrophil, eosinophil, monocyte and/or lymphocyte traits." (PMID 32600345, 2020).
depression (5 papers, 2022 to 2026). "Additionally, a meta-analysis of GWAS has indicated the association of BTN3A2 with neuroticism, which is an important risk factor for depression." (PMID 39897774, 2025). "Eight SNPs corresponding to six protein-coding genes (TNXB, NCAM1, LTBP3, BTN3A2, DAG1, FHIT) were identified that were highly associated with depression." (PMID 39897774, 2025). "We have identified six protein-coding genes associated with depression and primarily involved in inflammation (TNXB), neuroplasticity (NCAM1 and LTBP3), immune response (BTN3A2), cell survival (DAG1) and circadian clock modification (FHIT)." (PMID 39897774, 2025). "The present study identified six protein-coding genes associated with depression and primarily involved in inflammation (TNXB), neuroplasticity (NCAM1 and LTBP3), immune response (BTN3A2), cell survival (DAG1) and circadian clock modification (FHIT)." (PMID 39897774, 2025). "Our findings confirmed previous evidence for TNXB- and NCAM1 in the pathophysiology of depression and suggested four new potential candidate genes (LTBP3, BTN3A2, DAG1 and FHIT) that warrant further investigation." (PMID 39897774, 2025). "Our findings confirmed previous evidence for TNXB- and NCAM1 in the pathophysiology of depression and suggested new potential candidate genes (LTBP3, BTN3A2, DAG1 and FHIT) that warrant further investigation." (PMID 39897774, 2025). "Other potential candidate genes whose function might provide new insights in the pathophysiological process of depression include LTBP3, BTN3A2, DAG1 and FHIT." (PMID 39897774, 2025).
gastric cancer (4 papers, 2018 to 2021). A primary or metastatic malignant neoplasm involving the stomach. "Overexpression of the BTN3A2 gene is associated with increased proliferation and invasion of gastric cancer cells." (PMID 34565479, 2021). "This overexpression of BTN3A2 gene was associated with an increased proliferation and invasion of gastric cancer cells." (PMID 30050536, 2018). "In addition, BTN3A overexpression and a dominant expression of the BTN3A2 isoform were strongly associated with a poor prognosis, in gastric cancer and PDAC." (PMID 30050536, 2018). "Studies have shown that overexpression of BTN3A and dominant expression of BTN3A2 subtypes are closely related to the poor prognosis of pancreatic ductal adenocarcinoma and gastric cancer." (PMID 34565479, 2021). "BTN3A2 was the most expressed paralog along the BTN3A proteins in several AML, PDAC cell lines and primary tumors, and gastric cancer." (PMID 30050536, 2018). "BTN3A2 promoter and ORF were related also to gastric cancer and type I diabetes, respectively." (PMID 30050536, 2018).
triple-negative breast carcinoma (4 papers, 2020 to 2022). An invasive breast carcinoma which is negative for expression of estrogen receptor (ER), progesterone receptor (PR), and human epidermal growth factor receptor 2 (HER2). "Moreover, a recent study suggested that BTN3A2 serves as a prognostic marker and favors immune infiltration in triple-negative breast cancer." (PMID 34022836, 2021).
lung carcinoma (3 papers, 2018 to 2023). "Notably, increased expression of BTN3A2 is associated with a favorable prognosis in lung cancer." (PMID 37680636, 2023).
pancreatic ductal adenocarcinoma (3 papers, 2020 to 2021). An infiltrating adenocarcinoma that arises from the epithelial cells of the pancreas. "Besides, BTN3A2 also plays an important role in activating the phosphoantigen-mediated Vγ9Vδ2 T cells toward the development of pancreatic ductal adenocarcinoma (PDAC), implicating it as a promising immunotherapeutic target for the treatment of PDAC." (PMID 32754194, 2020).
autoimmune disease (2 papers, 2022 to 2024). A disorder resulting from loss of function or tissue destruction of an organ or multiple organs, arising from humoral or cellular immune responses of the individual to their own tissue constituents. "AS and RA are both autoimmune diseases; the CpG locus of the BTN3A2 gene may be related to AS, which provides a new research direction for the pathogenesis of AS." (PMID 35619696, 2022).
celiac disease (2 papers, 2018 to 2024). An autoimmune genetic disorder with an unknown pattern of inheritance that primarily affects the digestive tract. "For instance, we identified an association between rs72841509 in BTN3A2 and Celiac disease (coded malabsorption/celiac disease) in our initial GWAS (MAF = 0.13, p = 1.8 × 10−119, OR = 2.33, 95% CI: 2.17–2.50)." (PMID 29691392, 2018). "Of the 12 altered protein, 5 protein-disease causalities were supported by MR, i.e., LTA-celiac disease (PIVW = 1.29 × 10−3), IL18BP-Crohn’s disease (PIVW = 4.04 × 10−2), DDR1-Graves’ disease (PIVW = 3.37 × 10−3), CDSN-psoriasis (PIVW = 4.02 × 10−7), and BTN3A2-SD (PIVW = 3.93×10−5)." (PMID 39009607, 2024).
Crohn disease (2 papers, 2020 to 2024). A gastrointestinal disorder characterized by chronic inflammation involving all layers of the intestinal wall, noncaseating granulomas affecting the intestinal wall and regional lymph nodes, and transmural fibrosis. "Conversely, increased BTN3A2 expression was associated with increased risk of inflammatory bowel disease (IBD; 0.025), including Crohn’s disease (0.053), as well as risk of PBC (0.129), where PBC variants also showed colocalisation with BTN3A2 eQTLs." (PMID 32724101, 2020).
glioma (2 papers, 2022 to 2026). A benign or malignant brain and spinal cord tumor that arises from glial cells (astrocytes, oligodendrocytes, ependymal cells). "BTN3A2 is a multifunctional regulatory protein originally implicated in γδ T-cell-mediated immune responses, yet its tumor-intrinsic role and mechanistic relevance in glioma are poorly defined." (PMID 41965757, 2026). "Functional studies using lentivirus-mediated BTN3A2 knockdown demonstrated that BTN3A2 promotes glioma cell proliferation, migration, and invasion, and its depletion increases TMZ sensitivity in vitro and in vivo." (PMID 41965757, 2026). "Collectively, these findings establish BTN3A2 as a hypoxia-driven, cell-intrinsic mediator of glioma progression and chemoresistance, highlighting its potential value as a prognostic biomarker and therapeutic vulnerability." (PMID 41965757, 2026). "High BTN2/3 expression was correlated with OS among sexes (except BTN3A3 in women), WHO grade II (BTN2A2), III (BTN2A2, BTN3A1, and BTN3A2), and IDH-Mut (BTN2A2 and BTN3A2) in glioma." (PMID 36033440, 2022).
type 1 diabetes (2 papers, 2023 to 2024). "BTN3A2, a gene of the extended class I region of the major histocompatibility, is associated with type 1 diabetes." (PMID 37224769, 2023).
allergic disease (1 paper, 2020). An immune response that occurs following re-exposure to an innocuous antigen, and that requires the presence of existing antibodies against that antigen. "We found strong causal effects of neonatal BTN3A2 expression on various autoimmune and allergic diseases." (PMID 32724101, 2020).
ischemic stroke (1 paper, 2025). A stroke disorder caused by obstruction of blood flow to the brain, due to thrombotic (local blood clot formation) or embolic (due to a blood clot or other material traveling from another site) event. "Based on the MR results and literature review, we proposed that higher BTN3A2 levels may decrease the risk of ischemic stroke by dampening detrimental immune reactions that may exacerbate ischemic injury." (PMID 40657554, 2025). "Among the novel candidate causal genes to highlight, BTN3A2 showed a relatively large effect on ischemic stroke, and the significant result was consistent across different datasets and methods, suggesting a crosstalk between immune modulation and stroke pathogenesis." (PMID 40657554, 2025). "BTN3A2 was highlighted as a novel candidate gene for ischemic stroke, suggesting a crosstalk between immune modulation and stroke pathogenesis." (PMID 40657554, 2025). "Among these potential novel therapeutic targets, BTN3A2 stands out as a promising target for ischemic stroke." (PMID 40657554, 2025). "Among novel targets, BTN3A2 had a relatively large protective effect on ischemic stroke, and the results were consistent across 4 MR methods with balanced horizontal pleiotropy tested with MR Egger intercept." (PMID 40657554, 2025).
lung adenocarcinoma (1 paper, 2022). A carcinoma that arises from the lung and is characterized by the presence of malignant glandular epithelial cells. "However, the relation with infiltrating immune and prognosis of BTN3A2 in lung adenocarcinoma are not clear." (PMID 35873496, 2022).
lung squamous cell carcinoma (1 paper, 2022). "The results illustrated that the BTN3A2 expression was lower in LUAD, lung squamous cell carcinoma, as well as kidney renal clear cell carcinoma than that in the non-malignant tissues." (PMID 35873496, 2022).
membranous nephropathy (1 paper, 2024). "In addition, we observed that BTN3A2, BTN3A3, and MICB decreased the risk of membranous nephropathy, but sRAGE and AIF1 increased this risk." (PMID 38898508, 2024).
Nephropathy (1 paper, 2023). A nonspecific term referring to disease or damage of the kidneys. "Tag-SNPs captured by SLC17A3 rs942379 variant additionally impacts the expression of BTN3A2 in glomerulus and those captured by TATDN2 rs394558 variant combinedly affects the expression of ATP2B2 in glomerulus further elucidating its role in nephropathy related traits." (PMID 37696853, 2023).
pulmonary diseases (1 paper, 2022). "These genes include the long non-coding gene LINC01278 and some other genes known to be involved in the interferon network but lacking understanding of their role in pulmonary diseases, such as IDO1 and BTN3A2." (PMID 36203777, 2022).
sarcoidosis (1 paper, 2023). Sarcoidosis is a multisystemic disorder of unknown cause characterized by the formation of immune granulomas in involved organs. "Our eQTL/GWAS analysis also identified rs2393915 in EAs with complicated sarcoidosis associated to BTN3A2, BTN3A3 and BTN2A3P, MHC I-associated genes; other BTNL2 polymorphisms (rs2076530, rs206530), have been previously reported associated to sarcoidosis susceptibility." (PMID 38390497, 2023). "The BTN3A2 and BTN3A3 genes in the butyrophylin family interactions pathway are known sarcoidosis candidate genes." (PMID 38390497, 2023).